INS (insulin)
Diseases named in the same sentence as INS in open-access papers (continued):
Sharing a sentence is not in itself a finding about the gene and the disease.
type 1 diabetes (continued). "Hence the current study was conducted to evaluate glucose lowering activity of a defined composition (UP780) of Aloe vera inner leaf gel powder (Qmatrix) with aloe chromones (aloesin) in insulin dependent alloxan induced type-1 diabetes model and non-diabetic healthy CD-1 mice." (PMID 24891878, 2014). "There might not be as many patients as are needed to answer a question such as: ‘does controlling type 1 diabetes by insulin pump rather than by injections lead to healthier newborns?' This clearly needs a study of diabetic women who are planning to have children, or have had children." (PMID 22518089, 2012). "However, the design of these trials should be based on the understanding that about 30% or more of relatives of type 1 diabetics might not develop an insulin requirement within 15 years." (PMID 21573001, 2011). "Participants with type 1 diabetes exhibited hepatic (EGP 64% higher), muscle (glucose infusion rate [GIR] 29% lower) and adipose (higher non-esterified fatty acids [NEFA]) insulin resistance." (PMID 41285865, 2025). "This approach clearly showed that under basal conditions, individuals with type 1 diabetes had a population enriched in CD62P (P3; CD62P+PAC-1−PS−), which was absent in those with normal insulin sensitivity." (PMID 40304758, 2025). "In conclusion, adults with type 1 diabetes starting Omnipod 5 use demonstrated a short-term improvement in key CGM-related metrics, without requiring an increase in insulin dosage." (PMID 41473236, 2025). "Thirty-two percent of the donors with type 1 diabetes were positive for IA2 and 64% were positive for GAD65 antibodies; none were anti-insulin positive." (PMID 38864887, 2024). "In the absence of endogenous insulin secretion, in type 1 diabetes (T1D), circulating IGFBP-1 concentrations are disproportionately increased in relation to whole-body insulin sensitivity, measured by a euglycemic hyperinsulinemic clamp." (PMID 39595651, 2024). "Additionally, our study showed that the stimulatory effect of adrenaline on glucagon secretion in physiological levels does not prevail over the suppressive effect of insulin, which may be highly relevant when individuals with type 1 diabetes experience insulin-induced hypoglycaemia." (PMID 38427076, 2024). "These oscillations in glycemic values are more important in Type 1 Diabetes Mellitus (T1DM), where the balance of glycemic values is much frailer due to the absolute absence of endogenous insulin." (PMID 38256584, 2024). "Few previous studies, which mainly based telemedicine on the adjustment of insulin treatment by FSG, have also demonstrated a noninferiority approach of TH in type 1 diabetes care regarding metabolic control and safety events." (PMID 37441496, 2023). "Since lack of insulin leads to type 1 diabetes, the effect of fermented SS on glucose uptake was also investigated in FL83B cells in the absence of insulin." (PMID 35893262, 2022). "Type 1 diabetes mellitus (T1DM) is one chronic autoimmune disease characterized by selective destruction of pancreatic β-cells driven by autoimmunity, thereby leading to absolute lack of insulin secretion and hyperglycemia." (PMID 35103245, 2022). "The second case is that of a 41-year-old male with a history of type I diabetes mellitus who presented with DKA and had no improvement despite aggressive resuscitation with fluids and insulin therapy." (PMID 36249626, 2022). "It is important to note that the term of T1D referred here is specifically for the state of untreated insulinopenic diabetes induced by STZ, which is distinct from the typical type 1 diabetes in humans that receive insulin treatments with largely controlled glucose levels." (PMID 33976218, 2021). "Our model, being a type 2 rather than type 1 diabetes-induced DKD model, corroborates the fact that our animals remained insulin-independent throughout the study." (PMID 34884571, 2021).
type 1 diabetes (continued). "In contrast, placentas of women with diabetes type 1, type 2, and GDM display normal levels of VE-cadherin in the chorionic vessels if not treated with insulin." (PMID 33578631, 2021). "Type 1 diabetes (T1D) is characterized by destruction of pancreatic β-cells and consequent lack of adequate endogenous insulin production to regulate blood glucose, for which values outside of a certain range may lead to health complications." (PMID 35392357, 2021). "IAH affects 20%‐25% of all people with type 1 diabetes, and of concern, the incidence of IAH has not changed in the last 2‐3 decades despite the introduction of insulin analogues and improved insulin delivery systems." (PMID 33532608, 2021). "The group of Denise Faustman used an agonistic TNFR2-selective antibody to demonstrate that a subpopulation of insulin-specific CD8+, but not CD4+, T cells in blood samples from patients with type 1 diabetes was vulnerable to TNFR2 induced death." (PMID 32528961, 2020). "The results of glucose, insulin and C-peptide in the oral glucose tolerance test (OGTT) performed were not consistent with a type 1 diabetes." (PMID 31956423, 2020). "It affects 25% of all people with type 1 diabetes and, of concern, the incidence of IAH has not changed in the last 2–3 decades despite the introduction of insulin analogues and improved insulin delivery systems." (PMID 31942669, 2020). "Type 1 diabetes (T1D) is a common autoimmune disease primarily mediated by T cells responses against pancreatic islet β-cell autoantigens, leading to the destruction of β cells and lack of insulin secretion." (PMID 32399500, 2020). "Type 1 diabetes (T1DM) is an autoimmune disease, also known as insulin-dependent diabetes mellitus, owing to the complete absence of insulin secretion." (PMID 33133095, 2020). "Type 1 diabetes mellitus (T1DM) resulted from the destruction of pancreatic beta cells and lack of insulin." (PMID 31775219, 2019). "One of the hallmarks of type 1 diabetes (T1D) in both human patients and nonobese diabetic (NOD) mice is the destruction of the insulin-producing β-cells in the pancreatic islets." (PMID 30817223, 2019). "In the past, when no insulin was available, LCD has been advocated as a treatment for type 1 diabetes (T1D), but the dietary recommendations of those times were quite different from the low carb/high fat diets recommended today." (PMID 31035514, 2019). "He developed insulin-dependent diabetes at 3 years of age with low C-peptide, and negative anti-GAD and anti-insulin antibodies." (PMID 29225575, 2017). "Direct comparison between type 1 diabetes and healthy non-diabetic individuals is challenging, as CHO intake elicits endogenous insulin secretion in the latter, which is the main determinant in fuel selection." (PMID 28230765, 2017). "Although this may detect patients who are miscoded, for example as having type 1 diabetes but are not on insulin 10 years postdiagnosis, it is less likely to detect patients who are misdiagnosed, for example in receiving insulin despite high endogenous insulin levels several years after diagnosis." (PMID 27080317, 2016). "Twenty KPDM patients and twelve type 1 diabetic patients (T1DM), evaluated at baseline, 12 and 24 months with/without insulin maintenance underwent a standardized mixed-meal tolerance test (MMTT) for 2 h." (PMID 25275325, 2014). "In type 1 diabetes mellitus (T1DM), with insufficient insulinization of the liver due to lack of endogenous insulin in the portal vein, there appears to be a dysfunction of the GH–IGF1 axis." (PMID 24327601, 2014). "Furthermore, available trials on CSII in type 1 diabetes are performed on patients who do not reach a satisfactory glycemic control with traditional insulin therapy; therefore, their characteristics may differ from the average of individuals with type 1 diabetes." (PMID 24170982, 2013).
type 1 diabetes (continued). "Type 1 diabetes mellitus (T1DM) is an autoimmune disease defined by hyperglycemia and hypoinsulinemia in the absence of exogenous insulin treatment." (PMID 23951058, 2013). "The presence of the TSHr-Ab as the only marker of thyroid autoimmunity has been described previously for a population of type 1 diabetes patients; however, GAD65-Abs were negative in our patients, and there is no need at present for insulin therapy." (PMID 22654905, 2012). "CONCLUSIONS: This study highlights that independent insulin pump or CGM use can mitigate the negative impacts of social vulnerability and race on long term glycemic control in youth with type 1 diabetes, emphasizing the need for greater access to these essential technologies." (PMID 41580661, 2026). "Type 1 diabetes was chemically induced (via STZ) in our mouse model and outcomes were monitored over 28 days, which is nearing the limit that the animals can survive without treatment of exogenous insulin." (PMID 40429969, 2025). "Managing type 1 diabetes mellitus (T1DM) can be challenging, as insulin therapy effectively controls blood glucose levels but is not curative, and sporadic, potentially fatal hypoglycemic episodes may still occur." (PMID 41364309, 2025). "To clarify whether the effect occurred without promoting insulin secretion, we examined whether the beneficial effect of HYA also occurred in type 1 diabetes model rats." (PMID 39899133, 2025). "Sometimes the complexity of new-generation systems such as “continuous subcutaneous insulin infusion, CSII” and patient or provider preference do not allow their use, so women with type 1 diabetes in pregnancy continue to be treated with subcutaneous multiple-injection insulin therapy using pens." (PMID 39791645, 2024). "In the matched type 1 diabetes group, we see a comparable metabolic control measured by HbA1c-values in people with GI and those without GI and a similar rate of CGM/FGM devices- and insulin pump use." (PMID 38317711, 2023). "In line herewith, in a similar STZ‐induced type 1 diabetes rat model Liraglutide was shown to normalise DM‐induced myocardial NAD(P)H oxidase activity, oxidative stress markers and apoptosis, without affecting plasma glucose and insulin levels." (PMID 35488737, 2022). "The role of insulin as a major autoantigen has been demonstrated in the Non-Obese diabetic (NOD) mouse, as the knockout of the insulin 1 gene prevents the development of type 1 diabetes while the knockout of the insulin 2 gene accelerates the disease process." (PMID 35937815, 2022). "This longitudinal observational study aims to evaluate real-word glycemic outcomes in children and adolescents with type 1 diabetes using three different CSII devices: hybrid closed-loop (HCL) systems, predictive low glucose (PLGS) systems, and non-automated insulin pumps." (PMID 36011925, 2022). "However, the low doses insulin requirement in a long period of time, more than 06 months, and the absence of DKA diminished the possibility of type 1 diabetes." (PMID 31956423, 2020). "The aim of the study was to develop a novel risk estimation model for predicting silent myocardial ischemia (SMI) in patients with type 1 diabetes (T1DM) and no clinical cardiovascular disease, evaluating the potential role of insulin resistance in such a model." (PMID 28369151, 2017). "The type 1 diabetes, previously called insulin-dependent diabetes mellitus (IDDM), is the consequence of progressive and selective destruction of pancreatic β cells by an immune-mediated process, resulting in an absolute lack of insulin." (PMID 15331022, 2004). "Unlike classical type 1 diabetes, ICI-DM often develops after only a few treatment cycles, shows a fulminant phenotype with disproportionally modest HbA1c elevation, and is typically irreversible and glucocorticoid-refractory, necessitating permanent insulin therapy." (PMID 41607457, 2026).
type 1 diabetes (continued). "Further, data presented of IAA prevalence in established type 1 diabetes should be interpreted with caution as antibodies may occur secondary to exogenous insulin administration and typically IAA should not be measured after two weeks of insulin treatment." (PMID 35185797, 2022). "Using a non-immune mediated streptozotocin model of type 1 diabetes, here we show that administration of an allosteric activator of SIRT1, SRT3025, led to substantial improvement in glycaemic control in the absence of any demonstrable effect on ß-cell mass, insulin secretion or insulin sensitivity." (PMID 30228292, 2018). "In how far type 1 diabetes affects the heart in the absence of CAD and hypertension remains controversial, mainly since results of human studies are ambiguous and since patients are usually treated with insulin which may attenuate or mask the phenotype." (PMID 27999359, 2016). "Furthermore, islet insulin and PC1/3 co-localisation was significantly reduced in donors with long-duration type 1 diabetes (0.845 vs 0.347 for non-diabetic donors vs donors with long-duration type 1 diabetes, respectively), suggesting reduced prohormone-processing capacity in residual beta cells." (PMID 39404844, 2024). "The effects of continuous subcutaneous insulin infusion (CSII) therapy with or without continuous glucose monitoring (CGM) on neonatal outcomes and glycemic outcomes of pregnant women with type 1 diabetes (T1D), living in Poland, were assessed." (PMID 36653533, 2023). "However, in an experimental model in rats with type 1 diabetes, maintenance of the action of the enzyme PFK‐1 and increase of intermediate products of the glycolytic pathway were observed, probably from some glucose uptake, regardless of insulin and adrenergic action." (PMID 33300293, 2021). "In addition, although type 1 diabetes mellitus (T1DM) is due to a relative lack of insulin, an increased prevalence of obesity and insulin resistance in this population means that NAFLD commonly coexists in patients with T1DM." (PMID 22110476, 2012). "Furthermore, since insulin only is not the usual treatment for T2DM treatment, these patients might have had specific clinical conditions where this type of treatment was indicated, such as misdiagnosed type 1 diabetes, secondary insulin insufficiency or end-stage organ failure." (PMID 34441749, 2021).
Hypoglycemia (5,833 papers, 1996 to 2026). A decreased concentration of glucose in the blood. "Nevertheless, since hypoglycemia unawareness is significant in patients with T2D in Saudi Arabia, with 50.5% of individuals with T2D using insulin in Madinah having hypoglycemia unawareness, reducing risk of hypoglycemia in these patients is essential." (PMID 41601933, 2026). "Age, hospitalization days, insulin regimen, fasting C-peptide, and fasting insulin were associated with hypoglycemia." (PMID 42273407, 2026). "Diagnostic evaluation revealed elevated insulin (47.8 μU/mL; reference range: 2-25 μU/mL) and c-peptide (11.2 ng/mL; reference range: 0.5-2 ng/mL) in the presence of hypoglycemia (serum glucose 42 mg/dL)." (PMID 42238165, 2026). "EIAS was diagnosed after the exclusion of other causes of hypoglycemia and with confirmation of very high insulin autoantibody levels, high plasma levels of bound insulin, and abnormal insulin clearance." (PMID 41472947, 2026). "Cognitive symptoms of mTBI, such as working memory and attention deficits, can be worsened by nocturnal hypoglycemia, increasing the risk of poor glycemic control due to challenges with dietary and insulin management." (PMID 42220685, 2026). "Hyperkalemia was also associated with hypoglycemia and azotemia (p < 0.0001), suggesting impaired renal potassium excretion and possible alterations in insulin-mediated cellular potassium uptake." (PMID 42121791, 2026). "This response can be beneficial in situations of higher hypoglycemia risk- such as during prolonged exercise or during the overnight period when insulin requirements fall." (PMID 41602572, 2026). "While incretin-based therapies, such as tirzepatide, are generally associated with a low risk of hypoglycemia, they can stimulate insulin secretion in susceptible individuals." (PMID 41356535, 2026). "The remaining 40% deploy machine- or deep-learning models to tackle harder problems, anticipating hypoglycemia, optimizing insulin dosing, estimating long-term complication risk, or extracting physiological signatures for personalized care." (PMID 41596449, 2026). "The efficacy studies showedthat casNP/insulin/C10 provided longer glycemic controland less risk of hypoglycemia than s.c.-injected IAsp for diabeticmice." (PMID 41442621, 2026). "We estimated transition probabilities of changes in hypoglycemia-associated medications (sulfonylureas and/or insulin) using a Markov model for each year of follow-up." (PMID 41893018, 2026). "Less insulin use lowers hypoglycemia risk, but its clinical relevance is limited in long-standing T1DM with low β-cell reserve." (PMID 41590243, 2026). "RCTs of adjunct liraglutide demonstrate weight loss and insulin-sparing effects but signal dose-dependent risks of hypoglycemia and ketosis." (PMID 41721160, 2026). "All types of insulin can be used at low doses, considering the risk of hypoglycaemia and individual HbA1c targets." (PMID 41536569, 2026). "Multivariable analysis identified T1DM, impaired renal function, and insulin or glinide use as factors significantly associated with hypoglycemia." (PMID 41971090, 2026). "Although the most common cause is insulin, insulinoma is a rare etiology, and hypoglycemia is often misdiagnosed as epilepsy." (PMID 42294457, 2026). "If the user forgets to do this, or is not able to predict their exercise bout, the high circulating insulin poses a risk of hypoglycemia." (PMID 41602572, 2026). "Once-weekly basal insulin provides glycemic control comparable to daily basal insulin, with modest improvements in glycemic outcomes and similar hypoglycemia risk." (PMID 42277362, 2026). "A larger meta-analysis of 1248 neurocritical care patients further demonstrated that intensive insulin therapy raises the risk of hypoglycemia and offers minimal mortality benefit." (PMID 39982264, 2025).